ETV4 (ETS variant transcription factor 4)
Diseases named in the same sentence as ETV4 in open-access papers (continued):
Sharing a sentence is not in itself a finding about the gene and the disease.
cancer (continued). "To better understand the prognostic value of ETV4 in different cancer types, we investigated correlations between ETV4 expression and survival outcomes for each cancer using Cox regression and Kaplan-Meier survival analysis." (PMID 37205199, 2023). "Taken together, the present results demonstrate that ETV4 is upregulated in multiple cancers and that high expression of ETV4 is correlated with cancer progression and undesirable survival outcomes." (PMID 37205199, 2023). "The overexpression of ETV4 promotes cell proliferation by upregulating cancer-related genes and the epithelial–mesenchymal transition (EMT) by activating EMT-specific transcription factors." (PMID 36289913, 2022). "As a member of the ETS transcription factor family, ETV4 is a key regulatory protein that can change the hundreds of genes expression in various cancers." (PMID 35121725, 2022). "The RAS-RAF-MEK-ERK (MAPK) signaling pathway and PI3K/Akt signaling can activate ETV4 expression in cancer." (PMID 35280808, 2022). "Cellular signaling pathways altered in ETV4-fusion-positive cancer were validated by analyzing microarray data from a previous study." (PMID 36289913, 2022). "In this study, we report that ETV4 is a critical transcription factor for metabolic rewiring in cancer cells, it promotes the transcription of hexokinase 2 (HK2) and lactate dehydrogenase A (LDHA), two enzymes indispensable for efficient glycolytic flux." (PMID 34052833, 2021). "To date, little is known about the roles of ETV4 in cancer cell energy metabolism and maintenance of cancer stemness." (PMID 34052833, 2021). "In light of the function of glycolysis to support synthesis of macromolecules essential for cell proliferation, it is reasonable to expect that downregulation of ETV4 to disrupt glycolytic flow will hinder cancer cell growth." (PMID 34052833, 2021). "To investigate the glycolytic effect of ETV4 expression in cancer tissues, we performed gene set enrichment analysis (GSEA) by exploiting The Cancer Genome Atlas (TCGA) RNA-sequencing data." (PMID 34052833, 2021). "Other research documents that siRNA-mediated knockdown of ETV4 results in reduced cancer cell proliferation and invasion." (PMID 33407520, 2021). "Our results suggest that expression levels of SPRY2 and ETV4 are likely indicative of the sensitivity of cancer cell lines to many MAP kinase inhibitors." (PMID 33858332, 2021). "Taken together, these data suggested that ETV4 was essential for PD-L1L2-SE-mediated PD-L1/L2 expression in cancer cells." (PMID 34623791, 2021). "The EMT, angiogenesis and cancer progression induced by miR-29b inhibitor were reversed by siRNA-mediated ETV4 silencing." (PMID 33407520, 2021). "Our present rescue experiments further confirmed that siRNA-ETV4 neutralized the promotion of cancer progression induced by miR-29b inhibitor, suggesting that inhibition of ETV4 conferred a suppressive role of miR-29b in CRC progression." (PMID 33407520, 2021). "Together, our study highlights the potential roles of ETV4 in promoting cancer cell glycolytic shift and BCSC maintenance and reveals the molecular basis." (PMID 34052833, 2021). "Other transcription factors are associated with cancer-related pathways, such as NPAT, ZNF264, HEYL and ETV4." (PMID 33525507, 2021). "Among these, ETV4 has been widely reported to play oncogenic roles in numerous cancers such as papillary thyroid carcinoma, renal cell carcinoma, gastric cancer, lung cancer, and breast cancer." (PMID 34623791, 2021). "Some of the other enriched transcription factors include MYB, BRCA1, STAT1 and ETV4 which are upregulated in majority of the cancer types." (PMID 34728699, 2021). "Our rescue experiments further demonstrated that the promotion of cancer progression induced by miR-29b inhibitor was neutralized by siRNA-ETV4, suggesting that inhibition of ETV4 conferred the suppressive role of miR-29b in CRC progression." (PMID 33407520, 2021).
cancer (continued). "Existing studies have found that ETV4’s ability to promote cancer migration is closely related to MMP." (PMID 34820188, 2021). "Our findings also highlight ETV4 as a strong promoter of cancer progression as well as a critical target of CIC in the context of CRC." (PMID 32042269, 2020). "Either mutations in or loss of CIC can promote cancer progression via upregulating the expression of PEA3 group genes (ETV1/ER81, ETV4/PEA3, and ETV5/ERM), the best characterized and reliable CIC target genes." (PMID 32042269, 2020). "Since Pea3/ETV4 is extensively studied with respect to its metastatic function in many cancers, common target genes identified in these tissues were matrix metalloprotease enzymes, particularly MMP1, MMP2, and MMP93." (PMID 33097800, 2020). "In both RWPE and PNT1A (two immortalized non-cancer human prostate cell lines), the overexpression of ETV4 reduced the luciferase expression from the CDKN1A promoter." (PMID 32791988, 2020). "As a counter-proof of the effects of ETV4 overexpression, we tested a human cancer prostate cell line, PC3, that has high basal levels of ETV4." (PMID 32791988, 2020). "ETV4 overexpression was found in two of the 106 cancer samples, both deriving from the same cancer focus." (PMID 31537872, 2019). "Depletion of ACLY protected cancer cells from hypoxia-induced apoptosis through modulating ETV4 via α-ketoglutarate." (PMID 31088900, 2019). "In order to determine if MMP13 participates in ETV4-regulated cancer cell properties, we repressed MMP13 in the ETV4-overexpressing MMT cell line." (PMID 29996935, 2018). "Of these primary cancers, 75% were classified into seven subtypes, defined by either specific gene fusions of ETS transcription family members (ERG, ETV1, ETV4, and FLI1) or mutations (SPOP, FOXA1, and IDH1)." (PMID 29581876, 2018). "Transcriptional adaptation to hypoxia is most often orchestrated by the HIFs; however, here we showed that cancer cells’ hypoxic survival can be mediated by a different transcription factor, ETV4." (PMID 26452058, 2015). "Furthermore, the phosphorylation regulation roles of ETV4 has also been reported in several cancers." (PMID 41318472, 2025). "In this study, we explored the expression and prognostic value of ETV4 across various cancers." (PMID 40469297, 2025). "More interestingly, some previous studies have verified that the expression of ETV4 could also be enhanced by ERK pathway in cancers." (PMID 41281746, 2025). "Among them, ETV4 plays a crucial role in cancer progression." (PMID 40469297, 2025). "Taken together, ETV4 could be a promising target of cancer therapy as a transcription factor, coactivator or chromatin modulator." (PMID 41281746, 2025). "We describe here the critical functions of the cancer‐driven gene ETV4 in DNA replication in NSCLC." (PMID 40548893, 2025). "Thus, a comprehensive analysis of ETV4 across a pan-cancer dataset is essential to uncover new strategies for cancer treatment." (PMID 40469297, 2025). "Our findings indicated that ETV4 enhances cancer cell migration and invasion by promoting epithelial-mesenchymal transition (EMT), which may trigger extracellular matrix degradation and anti-apoptotic pathways." (PMID 40469297, 2025). "Finally, given the heterogeneity of ETV4 expression and function across cancer types, its utility as a universal biomarker or therapeutic target should be evaluated with caution." (PMID 40469297, 2025). "ETV4, as a canonical transcription factor, could mediate the development and progression in multiple cancers through transcriptionally regulating its targeted genes, such as Cyclin D1, CXCR4, ANXA2 and KDM5D39-42." (PMID 41281746, 2025). "Additionally, increasing studies have identified that ETV4 promotes cancer growth, invasion, metastasis, and drug resistance." (PMID 37205199, 2023). "Increasing evidence supports a relationship between E twenty-six variant transcription factor 4 (ETV4) and several cancers, but no pan-cancer analysis has been reported." (PMID 37205199, 2023).
cancer (continued). "To determine whether high ETV4 protein expression alone is sufficient to drive progression to invasive cancer, we administered TAM in 6- to 8-week-old mice and aged them for 6, 9, and 12 months for phenotypic assessment." (PMID 37018402, 2023). "Moreover, ETS variant transcription factor 4 (ETV4) belongs to PEA3 subfamily of ETS transcription factor, a cancer-promoting transcription factor." (PMID 36845708, 2023). "Additionally, ImmuneScore and StromalScore were also employed to evaluate the relationship between ETV4 expression and immune cell infiltration among cancers." (PMID 37205199, 2023). "For many different cancers, patients with higher ETV4 expression had worse disease prognosis." (PMID 37205199, 2023). "It was observed that in cancer cells, ETV4 is expressed at a higher level compared to normal cells." (PMID 37174125, 2023). "ETV4 also acts as an oncogenic protein that can enhance cancer growth, progression, and metastasis." (PMID 37174125, 2023). "This suggests that our selected genes in the metabolism pathway could be possible therapeutic targets for ETV4-fusion-positive cancer." (PMID 36289913, 2022). "As ETV4 has been acknowledged as a master TF that drives PD-L1L2-SE, genetic silencing or pharmacological inhibition in cancer cells, we investigated whether ETV4 has a similar SE mechanism in HCC." (PMID 35121725, 2022). "Interestingly, ETV4 was also included in the 568 cancer driver gene pool obtained by the Integrative OncoGenomics pipeline." (PMID 35121725, 2022). "Overall, a disorder of downstream target genes expression has a crucial role in ETV4-driven tumors, and ETV4 target genes and signaling involved in the regulation of the potential cancer cells have been reported, including the activation of MMP1 and RAS/MAPK signaling." (PMID 35121725, 2022). "Finally, APDT led to up-regulation of developmental transcription factors involved in stem cells and cancer stem cells (ETV4, SOX9, FOXO1 and FOXO3)." (PMID 35328625, 2022). "Mutations and loss of CIC have been reported to promote the progression of various cancers via derepression of cancer-associated CIC target genes, including polyomavirus enhancer activator 3 (PEA3) group genes (ETS variant transcription factor 1 [ETV1], ETV4, and ETV5)." (PMID 36619173, 2022). "Interestingly, we observed statistical significance for the loss of internal degrons from several fusion genes, such as 5′ EML4 fusions, 3′ NSD1 fusions and the previously validated 3′ ETV4 fusions, only when considered in conjunction with cancer type." (PMID 34795215, 2021). "In contrast, ETV4 showed a ubiquitous expression pattern among all human cancer cell lines." (PMID 33628843, 2021). "In addition, ETV4 was found to promote the invasion and metastasis of cancer cells by promoting the greening of COX2." (PMID 34820188, 2021). "In addition, genomic and transcriptomic ETV4 gene fusions have been demonstrated in Ewing sarcoma and prostate cancer and suggested to have role in carcinogenesis of both cancer." (PMID 29467595, 2018). "In fact, MMP13 has the same behavior as ETV4 in these cancer cells but is less potent." (PMID 29996935, 2018). "DNA methylation cluster 1 contained twice the number of hypermethylated loci in comparison with cluster 3, and the epigenetic patterns were substantially different from those of ETV1- and ETV4-rearranged cancers, which exhibit more heterogeneous methylation levels." (PMID 29581876, 2018). "In addition, several studies have suggested that the pathways by which ETV4 promotes metastasis in various type of cancers include extracellular signal-regulated kinases signaling associated with matrix metalloproteinase enzyme." (PMID 29467595, 2018). "Specifically, we showed that blocking de novo lipogenesis through the genetic depletion of ACLY or ACC1 protected multiple cancer cells from hypoxia-induced apoptosis through increased levels of α-ketoglutarate and the inhibition of ETV4 and its transcriptional activities." (PMID 26452058, 2015).
cancer (continued). "ERG, ETV1, ETV4, ETV6, FLI1, and FEV, are implicated in the pathogenesis of several cancers." (PMID 21789226, 2011). "However, previous studies on ETV4’s function have been limited to specific cancer types." (PMID 40469297, 2025). "However, it remains uncertain whether ETV4 contributes to the etiology of various cancers through common molecular processes." (PMID 37205199, 2023). "However, it remains unclear whether ETV4 affects various cancers through common molecular processes." (PMID 37205199, 2023). "Next, we analyzed whether ETV4 is correlated with cancer cell stemness or proliferation." (PMID 26356813, 2015). "In this study, we demonstrated that the expression of ETV4 was remarkably upregulated in CRC tissues and significantly related to the lymph node metastasis and the stage of cancer." (PMID 41281746, 2025). "In the present study, we confirmed that the expression of ETV4 is indeed upregulated in CRC, which is closely related to lymph node metastasis and cancer stage." (PMID 41281746, 2025). "Although small, these differences affected important signaling pathways (NGF-stimulated transcription, IL-10 signaling, PERK activity) and cancer genes (CBFA2T3, ETV4, FGFR1, GLI1, SGK1, and STAT3)." (PMID 38968069, 2024). "ETV4 and FOXM1 are the two common overregulated TFs in the three types of cancer and are important in the regulation of other key TFs and DEGs, as well as the formation of co-regulatory complexes, during the tumorigenic process in the gut-lung axis." (PMID 39228892, 2024). "We identify SLFN11, ETV4, HNRNPA1, and CMTM7 as promising markers of drug sensitivity in a number of common cancers." (PMID 39494610, 2024). "Using the online tool GEPIA, we subsequently screened out four transcription factors (ETV4, FOXP3, E2F1 and XBP1) which are highly expressed in CRC and closely related to cancer." (PMID 38041531, 2024). "Here, we reported that variations in ETV1, ETV4, and ETV5 expression level correlated with prognosis in different types of cancer including CRC." (PMID 35860243, 2022). "For the LUAD network, four TFs, ETV1, ETV4, ETV6, and ELK4, were involved in the pathway called “transcriptional mis-regulation in cancer”." (PMID 35524179, 2022). "Seven winning TFs (ETV4, ID2, MEIS1, NR4A3, RARA, TCF3, and ZBTB16) are related to transcriptional misregulation in cancer (p-value: 6.9 × 10−5)." (PMID 36101460, 2022). "In neurons, nerve growth factor (NGF) stimulates ETV4 expression through the ERK1/2 pathway, while it is regulated by both the ERK1/2 and SAPK/JNK pathways in cancer cells." (PMID 34381375, 2021). "ETV4 belongs to the PEA3 subfamily, which is known to promote tumor progression in several cancer types." (PMID 32982961, 2020). "Within this group we observed the ETV4, ETV5 and MYEOV genes which have been shown to promote resistance to MAP Kinase inhibitors as well as promoting cancer cell proliferation, invasion and migration." (PMID 30717152, 2019). "Third, the best known target genes of CIC include PEA3 group genes, ETV1/ER81, ETV4/PEA3, and ETV5/ERM, which are frequently overexpressed in several different types of cancers." (PMID 26124181, 2015). "In contrast, for chemokine receptors, ETV4 generally showed a negative correlation across most cancers." (PMID 40469297, 2025). "ETV4 and ETV5, members of the ETS family, are crucial in cancer biology." (PMID 40536817, 2025). "Although ETV4 overexpression leads to the development of mPIN, it does not directly result in cancer progression." (PMID 40469297, 2025). "Studies have shown that ETV1, ETV4, and ETV5 are highly expressed in a variety of cancers." (PMID 39668941, 2025). "ETV4 expression was significantly negative correlated with most of immune cell infiltration in cancers." (PMID 37205199, 2023). "A previous study in cancer cell lines reported that αvβ3 integrin signaling might activate the ERK pathway, resulting in ETV4 transcription, PD-L1/L2 expression, and evasion attacks from the immune system." (PMID 37234529, 2023).
cancer (continued). "The relationship between ETV4 and ICP genes varied among different cancer types." (PMID 37205199, 2023). "Considering that ASCL2 and ETV4 are upregulated in MSS CRC tissues in TCGA, we next investigated the expression of ASCL2 and ETV4 in MSS CRC cell lines and compared their expression with other cancer cell lines." (PMID 33628843, 2021). "Notably, the major PEA3 group members (e.g., ETV1, ETV4, or ETV5) regulated by CIC differ among cancer cell types; the expression of ETV5 and ETV4 is most highly and significantly upregulated by CIC deficiency in PC and HCC cell lines, respectively." (PMID 32238859, 2020). "Thus, similarly to ETV4, but with a weaker effect, MMP13 is an inducer of cancer cell proliferation, migration, and invasion." (PMID 29996935, 2018). "Moreover, cell proliferation, migration, invasion, anchorage-independent growth, and in vivo tumorigenicity were assayed using models of mammary epithelial and cancer cells in which the expression of MMP13 and/or ETV4 is modulated." (PMID 29996935, 2018). "ETV1, ETV4, ETV5, and ERG are members of the erythroblast transformation specific (ETS) transcription factor family and are well established as oncogenes in certain cancers, while ETV6 gene fusions have been reported in GIST." (PMID 29371979, 2017). "In addition, there are other transcription factors related to cancer and cell movement that are significantly upregulated in this model, including ELF3 (8.7X higher in DU145-LN4) and ETV4 (7.5X fold higher level in DU145-LN4 compared to DU145 cells)." (PMID 24885350, 2014). "Interestingly, several of these TFs (e.g., NKX3-1, SMAD1/3, SRF, ETV4 and ELK1) are known to play important roles in PCa, as well as in other types of cancer." (PMID 24968068, 2014). "However, compared with other ETS transcriptional factors, there is no data on the usage of alternative ETV4 transcripts in normal and cancer cells." (PMID 37002241, 2023). "ETV4 overexpression results in the development of mPIN but not in progression to cancer." (PMID 32791988, 2020). "Moreover, according to that ETV4 functions as a transcriptional factor, one of an interesting target for ETV4 is indoleamine 2,3-dioxygenase (IDO), an enzyme that involved in progression of many type of cancer." (PMID 29467595, 2018). "However, overexpression of miR-4516 did not influence TGF-β2-induced expression of SOX4, GRB2, and ETV4 in ARPE cells, although previous studies have reported that SOX4, GRB2, and ETV4 contribute to EMT in cancer cells." (PMID 35771766, 2022).
adenocarcinoma (4 papers, 2010 to 2023). A common cancer characterized by the presence of malignant glandular cells. "Among these DEG, the ETV4 stood out as one of the most expressed in the adenocarcinoma samples, further confirmed in the adenocarcinoma set of samples from the TCGA database." (PMID 33648461, 2021). "In both analyses, ETV4 was overexpressed in adenocarcinoma samples." (PMID 33648461, 2021). "Among those genes, ETV4 was further investigated and was shown to act on proliferation and migration of CRC cell lines, indicating that ETV4 could be a robust adenocarcinoma biomarker and a potential target for gene therapy studies in CRC." (PMID 33648461, 2021).